SMARCA4 (SWI/SNF related BAF chromatin remodeling complex subunit ATPase 4)
Description:
ATPase involved in transcriptional activation and repression of select genes by chromatin remodeling (alteration of DNA-nucleosome topology). Component of SWI/SNF chromatin remodeling complexes that carry out key enzymatic activities, changing chromatin structure by altering DNA-histone contacts within a nucleosome in an ATP-dependent manner. Component of the CREST-BRG1 complex, a multiprotein complex that regulates promoter activation by orchestrating the calcium-dependent release of a repressor complex and the recruitment of an activator complex. In resting neurons, transcription of the c-FOS promoter is inhibited by SMARCA4-dependent recruitment of a phospho-RB1-HDAC repressor complex. Upon calcium influx, RB1 is dephosphorylated by calcineurin, which leads to release of the repressor complex. At the same time, there is increased recruitment of CREBBP to the promoter by a CREST-dependent mechanism, which leads to transcriptional activation. The CREST-BRG1 complex also binds to the NR2B promoter, and activity-dependent induction of NR2B expression involves the release of HDAC1 and recruitment of CREBBP (By similarity). Belongs to the neural progenitors-specific chromatin remodeling complex (npBAF complex) and the neuron-specific chromatin remodeling complex (nBAF complex). During neural development, a switch from a stem/progenitor to a postmitotic chromatin remodeling mechanism occurs as neurons exit the cell cycle and become committed to their adult state. The transition from proliferating neural stem/progenitor cells to postmitotic neurons requires a switch in subunit composition of the npBAF and nBAF complexes. As neural progenitors exit mitosis and differentiate into neurons, npBAF complexes which contain ACTL6A/BAF53A and PHF10/BAF45A, are exchanged for homologous alternative ACTL6B/BAF53B and DPF1/BAF45B or DPF3/BAF45C subunits in neuron-specific complexes (nBAF). The npBAF complex is essential for the self-renewal/proliferative capacity of the multipotent neural stem cells. The nBAF complex along with CREST plays a role regulating the activity of genes essential for dendrite growth. SMARCA4/BAF190A may promote neural stem cell self-renewal/proliferation by enhancing Notch-dependent proliferative signals, while concurrently making the neural stem cell insensitive to SHH-dependent differentiating cues (By similarity). Acts as a corepressor of ZEB1 to regulate E-cadherin transcription and is required for induction of epithelial-mesenchymal transition (EMT) by ZEB1. Binds via DLX1 to enhancers located in the intergenic region between DLX5 and DLX6 and this binding is stabilized by the long non-coding RNA (lncRNA) Evf2 (By similarity). Binds to RNA in a promiscuous manner (By similarity). In brown adipose tissue, involved in the regulation of thermogenic genes expression (By similarity).
Synonyms: BAF190A; BRG1; SNF2L4; hSNF2b; BAF190; SNF2; SWI2; SNF2-BETA; SNF2LB; FLJ39786; CSS4; MRD16; OTSC12; RTPS2
Tractability: Small molecule: a structure with a bound ligand is known; a high-quality ligand is known; it has a binding pocket of medium quality. PROTAC: it is named in the literature on targeted protein degradation; UniProt records ubiquitination sites on it; ubiquitination databases record sites on it; its protein half-life has been measured; a small molecule that binds it is known.
Target class: Epigenetic regulator; Bromodomain; Reader
Chemical probes: ACBI1 (high quality), FHT-2344 (high quality), GNE-064 (high quality), PD127913, PFI-3 (high quality), SGC-SMARCA-BRDVIII (high quality)
Gene: Protein-coding gene on chromosome 19 (10,960,824 to 11,079,426, forward strand). Ensembl gene ENSG00000127616.
Subcellular location: Nucleus
Subcellular location (Human Protein Atlas): Nucleoli fibrillar center; Nucleoli rim; Nucleoplasm
Pathways (Reactome):
Chromatin organization: Chromatin modifying enzymes; Formation of neuronal progenitor and neuronal BAF (npBAF and nBAF); Formation of the canonical BAF (cBAF) complex; Formation of the embryonic stem cell BAF (esBAF) complex; Formation of the non-canonical BAF (ncBAF) complex; Formation of the polybromo-BAF (pBAF) complex; RMTs methylate histone arginines
Developmental Biology: Differentiation of naive CD4+ T cells to T helper 2 cells (Th2 cells); EGR2 and SOX10-mediated initiation of Schwann cell myelination; Regulation of MITF-M-dependent genes involved in pigmentation
Gene expression (Transcription): RUNX1 interacts with co-factors whose precise effect on RUNX1 targets is not known; Regulation of endogenous retroelements by Piwi-interacting RNAs (piRNAs)
Cell-Cell communication: Negative Regulation of CDH1 Gene Transcription
Immune System: Interleukin-7 signaling
Signal Transduction: Formation of the beta-catenin:TCF transactivating complex
Gene Ontology:
Molecular function: ATP hydrolysis activity; ATP-dependent activity, acting on DNA; ATP-dependent chromatin remodeler activity; DNA polymerase binding; identical protein binding; nuclear androgen receptor binding; nucleosomal DNA binding; protein binding; RNA polymerase I core promoter sequence-specific DNA binding; Tat protein binding; transcription coactivator activity; transcription coregulator binding; transcription corepressor activity; helicase activity; ATP binding; chromatin binding; histone binding; lncRNA binding; RNA polymerase II cis-regulatory region sequence-specific DNA binding; RNA polymerase II transcription regulatory region sequence-specific DNA binding
Biological process: chromatin remodeling; host-mediated activation of viral transcription; negative regulation of androgen receptor signaling pathway; negative regulation of cell growth; negative regulation of DNA-templated transcription; neural retina development; positive regulation of DNA-templated transcription; positive regulation of glucose mediated signaling pathway; positive regulation of miRNA transcription; positive regulation of transcription by RNA polymerase II; positive regulation of transcription of nucleolar large rRNA by RNA polymerase I; positive regulation of Wnt signaling pathway; negative regulation of cell differentiation; negative regulation of transcription by RNA polymerase II; positive regulation of cell differentiation; positive regulation of cell population proliferation; positive regulation of cold-induced thermogenesis; positive regulation of double-strand break repair; positive regulation of myoblast differentiation; positive regulation of stem cell population maintenance; positive regulation of T cell differentiation; regulation of G0 to G1 transition; regulation of G1/S transition of mitotic cell cycle; regulation of mitotic metaphase/anaphase transition; and 6 more
Cellular component: chromatin; extracellular region; fibrillar center; membrane; npBAF complex; nucleolus; nucleoplasm; nucleus; protein-containing complex; SWI/SNF complex; bBAF complex; GBAF complex; kinetochore; nBAF complex; nuclear matrix; RSC-type complex; euchromatin; perichromatin fibrils
Genetic constraint (gnomAD): Loss-of-function variants: 31 observed, 184.77 expected, observed/expected ratio (o/e) 0.17, 90% interval 0.12 to 0.23. The upper end of that interval is the gene's LOEUF score, 0.23, which puts it in group 1 of 6, group 1 being the genes least tolerant of losing a copy. Missense variants: 1,133 observed, 2,286.7 expected, observed/expected ratio (o/e) 0.5, 90% interval 0.47 to 0.52. Synonymous variants: 929 observed, 934.19 expected, observed/expected ratio (o/e) 0.99, 90% interval 0.94 to 1.05.
Gene-disease validity (ClinGen):
ClinGen rates the evidence that SMARCA4 causes each of these diseases.
Coffin-Siris syndrome (autosomal dominant): Definitive. Coffin-Siris syndrome (CSS) is a rare congenital multi-systemic genetic disorder characterized by aplasia or hypoplasia of the distal phalanx or nail of the fifth digit, developmental delay, intellectual disability, coarse facial features, and other variable clinical manifestations.
rhabdoid tumor predisposition syndrome 2 (autosomal dominant): Definitive.
hereditary nonpolyposis colon cancer (autosomal dominant): Limited.
Cancer hallmarks: cell replicative immortality (suppresses); invasion and metastasis (promotes); escaping programmed cell death (promotes); change of cellular energetics (promotes); genome instability and mutations (suppresses); suppression of growth (promotes); angiogenesis (promotes); invasion and metastasis (suppresses); tumour promoting inflammation; proliferative signalling (promotes); tumour promoting inflammation (suppresses); escaping immune response to cancer
Homologues: Orthologues: chimpanzee SMARCA4 (100% identical), macaque SMARCA4 (100% identical), pig SMARCA4 (99% identical), dog SMARCA4 (99% identical), rat Smarca4 (99% identical), guinea pig SMARCA4 (98% identical), mouse Smarca4 (97% identical), rabbit SMARCA4 (90% identical), tropical clawed frog smarca4 (88% identical), zebrafish smarca4a (88% identical), zebrafish SMARCA4 (79% identical). Paralogues in human: SMARCA2 (75% identical), CHD7 (22% identical), EP400 (22% identical), CHD2 (21% identical), CHD1 (21% identical), SRCAP (21% identical), CHD5 (21% identical), CHD9 (21% identical), CHD3 (20% identical), CHD8 (20% identical), CHD4 (20% identical), CHD6 (19% identical), and 18 more.
Diseases named in the same sentence as SMARCA4 in open-access papers:
SMARCA4 is named in the same sentence as 440 diseases in open-access papers, as found by Europe PMC text mining. Sharing a sentence is not in itself a finding about the gene and the disease. The quoted sentences say what the papers report.
lung carcinoma (167 papers, 2009 to 2026). "Approximately 10% of NSCLCs exhibit SMARCA4 deficiency, with mutations detected in 24% of lung cancer cell lines." (PMID 41577374, 2026). "Because of the scarcity of thoracic SMARCA4‐UT data in the database, we analyzed SMARCA4 mutations in lung cancer as a surrogate for this tumor type to some extent." (PMID 41577374, 2026). "In summary, the interaction between ALK mutations and SMARCA4 deficiency in NSCLC highlights the complexity of lung cancer biology." (PMID 40416876, 2025). "Previous studies have shown that SMARCA4 mutations in lung cancer co-segregate with other clinically important genes." (PMID 39888726, 2025). "The function of SMARCA4 varies among different organs and diseases, and SMARCA4 inactivation in lung cancer is related to the loss of lung lineage transcription and early metastasis." (PMID 38710944, 2025). "Here, we describe a rare case of small cell lung cancer (SCLC) with SMARCA4 loss, characterized by an aggressive phenotype, and further discuss the molecular, pathological, and clinical features of SMARCA2 and SMARCA4 deficiency in lung cancer." (PMID 39888726, 2025). "It is noteworthy that SMARCA4 loss in human lung cancer is associated with enhanced NRF2 target expression; this effect can be recapitulated in vitro where SMARCA4 knockdown inactivates KEAP1, activates NRF2 and enhances haem oxygenase 1 expression." (PMID 40069402, 2025). "Screening of the entire coding sequence of SMARCA4 in 59 lung cancer cell lines revealed mutations in 24% of the cell lines, which were much more common in NSCLC (35%) than in SCLC (5%)." (PMID 39888726, 2025). "Thoracic SMARCA4-deficient undifferentiated tumor (SMARCA4-dUT) is a recently described type of lung cancer, presenting as a bulky mass variably involving the mediastinum and the lung in patients with smoking history, and exhibits adverse prognosis." (PMID 40909976, 2025). "Meanwhile, only one case of SMARCA4-deficient SCLC receiving an ICI has been reported, highlighting the need for further research on the efficacy of immunotherapy in all types of lung cancer with the loss of SMARCA4." (PMID 39888726, 2025). "The final diagnosis was SMARCA4-deficient left lung cancer, classified as cT2aNxM1c, with metastasis to the right adrenal gland and brain, designated as stage IVB." (PMID 41142791, 2025). "Previous studies have shown that SMARCA4 mutations in lung cancer cells enhance OXPHOS activity and ROS production." (PMID 41392981, 2025). "The concomitant loss of SMARCA4 in NSCLC presents a complex aspect of the pathogenic mechanisms underlying lung cancer." (PMID 40416876, 2025). "Inactivation of SMARCA2 and SMARCA4 in a mouse model resulted in accelerated lung tumor development and loss of differentiation, closely resembling human lung cancer characterized by local tumor invasion and distant metastasis." (PMID 39888726, 2025). "Pathological tissue sections and imaging analyses indicated that both patients had SMARCA4-deficient undifferentiated lung malignant tumors." (PMID 41142791, 2025). "In conclusion, the interplay between EGFR mutation and SMARCA4 deficiency in NSCLC underscores the complexity of lung cancer biology." (PMID 39465834, 2024). "About 10% of lung cancer patients harbor SMARCA4 mutations, with different clinical features depending on the kind of mutation." (PMID 38542211, 2024). "From the histopathological point of view, there have been several improvements in the classification of lung cancer, with the description also of rare subtypes, such as SMARCA4-deficient undifferentiated tumors." (PMID 39335769, 2024). "Concurrent EGFR mutation and SMARCA4 deficiency in NSCLC present a complex scenario in lung cancer pathogenesis." (PMID 39465834, 2024). "SMARCA4-deficient thoracic tumors are a relatively new classification of mediastinal lung cancers that are known to be difficult to diagnose with conventional endobronchial ultrasound-transbronchial needle aspiration (EBUS-TBNA)." (PMID 39886719, 2024).
lung carcinoma (continued). "In this regard, IACS‐010759 treatment induced cell death in lung cancer cells harboring mutations in SMARCA4 or ARID1A." (PMID 38214418, 2024). "We selected 366 LUAD samples from two lung cancer immunotherapy datasets in cBioPortal; 15% (55/366) of the patients had SMARCA4 mutations, including 32 patients (9%) with driver mutations." (PMID 39322625, 2024). "Here we uncover a metabolic shift induced by SMARCA4/2-dual loss in ovarian and lung cancers that can be exploited therapeutically." (PMID 37210563, 2023). "SMARCB1-deficient tumors show sensitivity to inhibition of the proteasome machinery and autophagy pathways, while SMARCA4 mutated lung cancer cells have increased oxygen consumption and enhanced respiratory capacity." (PMID 37093326, 2023). "SMARCA4 inactivating mutations in lung cancers increase their sensitivity to CDK4/6 and Aurora Kinase inhibition." (PMID 37093326, 2023). "To improve the understanding of special types of tumors, we summarized and analyzed the clinicopathological features and prognostic factors of SMARCA4‐deficient non‐small cell lung cancer (SMARCA4‐dNSCLC)." (PMID 37184108, 2023). "Approximately 83% of patients with SMARCA4‐deficient non‐small cell lung cancer (SMARCA4‐dNSCLC) are at stage IV at the time of discovery, with a median progression‐free survival time of only 30 days." (PMID 37184108, 2023). "Fortunately, they found the compound 14, a dual allosteric small-molecule inhibitor that can block both SMARCA2 and SMARCA4 ATPase activity, thus exhibiting striking effects on SMARCA4-deficient lung-cancer models." (PMID 36361605, 2022). "Lung cancer cells with SMARCA4 mutations appear to be sensitive to inhibiting oxidative phosphorylation." (PMID 35342659, 2022). "Mutations in other tumor suppressors (RB1, CDKN2A, SMARCA4/BRG1) are also frequently implicated in lung cancer." (PMID 35573694, 2022). "SMARCA4 deficiency is observed in about 5% of conventional non‐small cell lung cancers, which should be distinguished by epithelial architecture, diffuse strong keratin expression and ancillary marker including SMARCA2." (PMID 35822082, 2022). "The special relationship carried by KRAS-driven lung cancers with SMARCA4 loss was studied by some research groups." (PMID 34440689, 2021). "In a recent genomic landscape study of SMARCA4 alteration and its association with the outcome involving 4813 lung cancer patients, SMARCA4-mutated NSCLC was divided into two clinically relevant genomic classes." (PMID 34440689, 2021). "The importance of identifying SMARCA4-deficient adenocarcinomas has gained interest for lung cancer management due to its aggressive behavior at diagnosis with vascular invasion and metastasis to the pleura seen upon presentation in most cases." (PMID 34440689, 2021). "In support of this, the loss or mutation of SMARCA4 is associated with human cancers including lung cancer, hepatocellular carcinoma, ovarian cancer, endometrial tumors, and Burkitt’s lymphoma." (PMID 33853662, 2021).